CDK10 (cyclin dependent kinase 10)
Diseases named in the same sentence as CDK10 in open-access papers (continued):
Sharing a sentence is not in itself a finding about the gene and the disease.
tumor (continued). "Finally, the highly complex contributions of ETS2 on the one hand, and of primary cilia on the other hand, will obviously complicate the elucidation of the role of CDK10/CycM in tumorigenesis and/or in tumor suppression." (PMID 28178678, 2017). "To determine whether CDK10 regulated tumor growth, we performed cell proliferation assays with GBC-SD and HCCC-9180 cells." (PMID 22209942, 2012). "Given that CDK10 is downregulated in clinical specimens and that it may act as a tumor suppressor, we decided to examine whether CDK10 had anti-oncogenic functions in BTC cells in vitro." (PMID 22209942, 2012). "Additionally, CDK10 expression was inversely correlated with tumor stage and lymph node metastasis." (PMID 34277407, 2021). "The fact that CDK10/CycM promotes ETS2 degradation and inhibits its transcriptional activity would support a tumor suppressor role of the kinase." (PMID 28178678, 2017). "Forty-seven tumor samples (including ICC, PCC, DECC, GBC and metastasis) were examined and showed that decreased CDK10 mRNA occurred in 36 of the 47 samples (76.6%), compared with normal tissue." (PMID 22209942, 2012). "A future challenge for drug development will be to design small molecules that target cell-cycle CDKs and transcriptional CDKs without inhibiting CDK10 and other CDKs that can act as tumor suppressors, such as CDK12." (PMID 32175313, 2020). "We showed that CDK10 was aberrantly expressed in BTC samples and cell lines, which demonstrates that expression of CDK10 is downregulated in BTC, and that it functions as a tumor suppressor to influence the cellular processes of BTC cells." (PMID 22209942, 2012). "Somewhat surprisingly, expression of a kd allele of murine CDK10 that is nearly identical to the longest human CDK10 isoform, did not inhibit tumor cell growth in a colony formation assay and did not affect the cell cycle profile of U2OS, NIH3T3 or L929 tumor cell lines." (PMID 28178678, 2017).
cancer (16 papers, 2012 to 2024). A tumor composed of atypical neoplastic, often pleomorphic cells that invade other tissues. "However, in our study expected consequence of enhanced ETS2 and cdk10 expressions at active phase of cell migration would be a decreased risk to develop certain types of cancers." (PMID 31413335, 2019). "Moreover, CDK10 is subject to a complex splicing process, and different splice variants might exert different and possibly opposite roles in cancer, as observed with other important proteins in tumorigenesis." (PMID 32175313, 2020). "From a mechanistic perspective, RNF115 activated the Raf-1 pathway and enhanced cancer cell cycle progression by degrading CDK10 in THCA cells." (PMID 38376606, 2024). "Previous studies have highlighted the dual roles of CDK10 that can function as tumor suppressor or oncogene in cancers." (PMID 38410280, 2024). "The methylation of CDK10 promoter or ubiquitination of CDK10 has been shown among the mechanisms of CDK10 regulation in cancers." (PMID 38410280, 2024). "This study infers a potential role for CDK10 in cancer metastasis, as inhibition of CDK10 resulted in a significant delay in corneal epithelial cell migration." (PMID 34277407, 2021). "Further studies are warranted to assess these as candidate binding partners for CDK10 in humans, and specifically, cancers involving the gastrointestinal tract and hepatobiliary system." (PMID 34277407, 2021). "CDK10 has been shown to be specifically involved in modulating cancer cell proliferation, motility and chemosensitivity." (PMID 34277407, 2021). "CDK10 small-molecule inhibitors would be useful in exploring the functions of this kinase and gauging its potential as a therapeutic target for some cancers." (PMID 32175313, 2020). "As with other CDK/cyclin kinases, many years of work will be necessary to achieve a clear understanding of the pleiotropic functions of the CDK10/CycM protein kinase and of its relevance as a potential therapeutic target and/or biomarker in cancers." (PMID 28178678, 2017). "First, the different splice isoforms of CDK10 are likely to play different, perhaps opposing roles, as frequently observed for many proteins exerting important functions in cancer." (PMID 28178678, 2017). "A number of transcriptomic and proteomic studies report upregulation of CDK10 in cancer cells or in cells exhibiting exacerbated division, and/or downregulation of CDK10 in differentiated cells." (PMID 28178678, 2017). "Although the roles of FGF18 and CDK10 in cell cycle progression and proliferation have been well studied, the relationship between their copy number and cancer survival is not fully understood." (PMID 26683928, 2015). "More interesting, an increase in c-RAF mRNA with a simultaneous decrease in CDK10 mRNA occurred in 33 of 47 (70.2%) cancer samples." (PMID 22209942, 2012). "If selective enough, such molecules will considerably help the exploration of the functions of CDK10/CycM, and they will also allow to determine whether it represents an interesting therapeutic target for some cancers." (PMID 32175313, 2020). "In these cancers, CDK10 expression levels may be indicative of chemoresistance." (PMID 34277407, 2021). "Little is known about PPIC in cancer, however PPIA and another PPIase PIN1 have been shown to interact with key growth and signalling proteins including cyclin D1, CDK10, cdc27, and PLK1, with diverse downstream effects on MAPK signalling." (PMID 27852308, 2016). "The concordance of these observations is challenged by a nearly equal number of studies that reveal downregulation of CDK10 messengers or protein in cancer cells and/or upregulation in non-dividing cells." (PMID 28178678, 2017).
cancer (continued). "Whereas CDK19 and CDK20 are not essential in any of the cancer cell lines tested, there is a minor proportion of cell lines in which CDK8 (~ 3%), CDK10 (~ 1%), CDK12 (~ 27%) and CDK13 (~ 3%) are essential." (PMID 36577800, 2022).
CDK10 also shares sentences with these, for which no sentence is quoted: basal cell carcinoma (2 papers); ciliopathy (2); Hydrocephalus (2); cardiomyopathy (1); colorectal adenocarcinoma (1); cutaneous melanoma (1); fetal hydrops (1); follicular lymphoma (1); Intellectual disability (1); invasive lobular breast carcinoma (1); keratinocyte carcinoma (1); lung adenocarcinoma (1); lymph node metastasis (1); multicystic dysplastic kidney (1); Myelodysplasia (1); neuroblastoma (1); osteochondropathies (1); Spastic paraplegia 7 (1); thyroid carcinoma (1).